KRTAP20-4 (keratin associated protein 20-4)
Description:
In the hair cortex, hair keratin intermediate filaments are embedded in an interfilamentous matrix, consisting of hair keratin-associated proteins (KRTAP), which are essential for the formation of a rigid and resistant hair shaft through their extensive disulfide bond cross-linking with abundant cysteine residues of hair keratins. The matrix proteins include the high-sulfur and high-glycine-tyrosine keratins (By similarity).
Synonyms: KAP20.4
Tractability: No criterion of Open Targets' tractability assessment is met for any kind of drug.
Gene: Protein-coding gene on chromosome 21 (30,620,627 to 30,620,850, forward strand). Ensembl gene ENSG00000206105.
Homologues: Orthologues: chimpanzee KRTAP20-4 (100% identical).